GRPR (gastrin releasing peptide receptor)
Diseases named in the same sentence as GRPR in open-access papers (continued):
Sharing a sentence is not in itself a finding about the gene and the disease.
tumor (continued). "With both Tle10 and NMe-His12 substitutions, the top candidate [68Ga]Ga-LW01110 has higher in vivo stability, tumor uptake and tumor-to-background uptake ratios than clinically validated [68Ga]Ga-RM2 and [68Ga]Ga-AMBA, and is promising for use for detecting GRPR-expressing tumors with PET." (PMID 38305955, 2024). "This assertion is supported by the results obtained from a comparative study between [68Ga]-PSMA-11 and [68Ga]-RM2 (GRPR detection) in patients with mCRPC, which have shown that [68Ga]-PSMA-11 tumor uptake was superior to that of [68Ga]-RM2 in most mCRPC lesions." (PMID 39598482, 2024). "Upon blocking of PSMA and GRPR, the tumour is no longer visualised and the kidneys are not as well defined." (PMID 36672390, 2023). "Further analysis revealed strong and GRPR-nonspecific binding of [111In]In-14 to necrotic tumor cores." (PMID 37046825, 2023). "The uptake of [68Ga]Ga-BQ7812 in the GRPR-blocked group was statistically significantly lower in the tumour and the pancreas compared with the non-blocked group." (PMID 36672390, 2023). "For primary PCa, the complementary value of GRPR targeting may also be found in the fact that we observed binding of [177Lu]Lu-NeoB and [177Lu]Lu-PSMA-617 to overlapping, but also to different tumor areas within the tumor region of one sample." (PMID 37719014, 2023). "Evidence was also provided by small-animal SPECT/CT scans with 177Lu-RM2 and 177Lu-AMTG over time, both of which showed high tumor retention and fast clearance from nontumor organs, even the GRPR-positive pancreas." (PMID 35027371, 2022). "68Ga-NeoBOMB1 is a novel GRPR radioligand suited for PET imaging and may deliver information on tumor vitality and burden in GIST patients and may increase sensitivity compared to contrast-enhanced CT." (PMID 36428467, 2022). "We assumed that metabolism in the pancreas is more rapid than in the tumor, which is why at early time points the less stable GRPR-targeted peptides exhibited an accelerated clearance from the pancreas but not from the tumor, compared to more stable analogues." (PMID 36145354, 2022). "have reported that GRP/GRPR is responsible for promoting the binding of CD16+ and CD94+ natural killer cells following inducing expression of Hsp72 by signaling via focal adhesion kinase, thus contributing to tumor cell cytolysis." (PMID 36518255, 2022). "According to the changes of the expression status of differential molecules between the two networks, we identified the top 10 differential mRNAs (PRKAA2, NLGN4X, ST6GALNAC3, DGAT1, TRIB1, GRPR, and MLLT11) and lncRNAs (n339695, n378130, and n410438) in the tumor–endothelium interaction." (PMID 33681194, 2021). "In orthotopic tumor tissues, 111In-JMV4168 bound with 2.2 ± 4% of added dose (%AD), whereas low binding was observed in the blocking group with 0.1% AD, confirming the specific binding of 111In-JMV4168 to GRPR ex vivo." (PMID 33986665, 2021). "In a following side-by-side comparison of [99mTc]Tc-DB1 with the agonist-based [99mTc]Tc-DB4, [99mTc]Tc-DB1, despite the lack of internalization, achieved higher tumor uptake and faster washout from GRPR-positive tissues." (PMID 34830920, 2021). "Although this feature went hand-in-hand with their lack of internalization in cancer cells, GRPR-radioantagonists did achieve significant uptake and retention in tumor lesions in mice and in patients." (PMID 34680243, 2021). "Patients with pPCa might profit from information given by tracers targeting GRPR and PSMA simultaneously, in terms of a better delineation of the gross tumor volume." (PMID 32533273, 2020). "Histopathology was used to examine the extent to which the single and combined image information of PET scans targeting GRPR and PSMA might lead to better tumor delineation." (PMID 32533273, 2020). "Already at 3 h p.i. both 55Co- and 64Cu-labeled conjugates allowed clear visualization of GRPR-expressing tumors because tumor activity uptake exceeded normal tissue uptake." (PMID 33352838, 2020).
tumor (continued). "The observed stabilization was shown to drastically improve the uptake of two representative radiopeptides, [99mTc]Tc-DB4 and [111In]In-SG4, in tumor-bearing mice via GRPR-/CCK2R-specific pathways, most probably by enhancing the supply of intact radiotracers to tumor-residing receptors." (PMID 33256013, 2020). "Tumor activity uptake of 111In-6 dropped by only 25%–30% when the targeted receptors were blocked individually, modeling a situation with PSMA-positive/GRPR-negative and PSMA-negative/GRPR-positive xenografts used in other published studies." (PMID 31540122, 2019). "For [111In]In-DOTA-PEG2-RM26, significant (p < 0.05) reduction of uptake for lung, pancreas, stomach, small intestine and tumour in the blocked group compared to non-blocked group was observed, indicating GRPR-specific accumulation of both radioconjugates." (PMID 31382362, 2019). "In agreement with our in vivo findings, tumor cells treated with high dose hyperthermia revealed a significant increase of GRPR expression and no alteration after low dose hyperthermia compared to controls." (PMID 28761146, 2017). "We have shown that contrast agents with a targeting peptide grafted in the loop region of ProCA1 have qualitatively better in vitro targeting abilities than those in which it is fused to the C-terminal of ProCA1 for GRPR expressed by both PC3 and DU145 tumor cells." (PMID 26577829, 2015). "By comparison, injection of ProCA1 without the GRPR targeting moiety or use of the clinical contrast agent Gd-DTPA to the tumor bearing mice did not result in any significant MRI contrast enhancement in tumor regions under the same conditions." (PMID 26577829, 2015). "Bronchial GRPR expression in non-cancerous mucosa was independent of disease stage (P = 0.49) and tumor histology (P = 0.50)." (PMID 22296774, 2012). "In addition to cancer-specific overexpression of GRPR, we have demonstrated that mucosal tissues adjacent to HNSCC have GRPR mRNA levels reflective of the adjacent HNSCC tumor." (PMID 22296774, 2012). "Finally, the heterodimer [RGD-Glu-(DO3A)-6-Ahx-RM2] labeled with 86Y/90Y exhibited high affinity for GRPR in PC-3 cells and rapid clearance from non-target tissue in tumor-bearing mouse." (PMID 40869454, 2025). "However, most clinically evaluated GRPR-targeted radiopharmaceuticals derived from BBN showed extremely high pancreas uptake, which not only limits the detection of GRPR-expressing tumor lesions in and near the pancreas but also lowers the maximum tolerated dose for radiotherapeutic applications." (PMID 40006047, 2025). "Therefore, GRPR radioantagonists with improved proteolytic stability and longer residence time in tumor foci with low uptake in non-target organs are currently being sought to improve the therapeutic efficacy." (PMID 41684873, 2025). "Therefore, CHO-K1-GRPR and CHO-K1-PSMA were assumed to represent an appropriate combination for the simultaneous establishment of GRPR+ and PSMA+ tumor xenografts in a mouse model, since they showed similar growth rate and expression density of the respective target." (PMID 40732291, 2025). "Imaging studies showed that the PC-3 tumor xenograft could be clearly visualized in PET images using all three 68Ga-labeled tracers ([68Ga]Ga-LW01158, [68Ga]Ga-LW01186, and [68Ga]Ga-LW02002), confirming their good in vivo GRPR-targeting capabilities." (PMID 38794191, 2024). "However, over years of research, many antagonistic ligands of GRPR have been discovered, which possess numerous advantages, such as efficient washout, a higher tumor/background ratio, and no side effects connected with GRPR activation." (PMID 38067350, 2023). "In order to address PCa tumor heterogeneity, given that their expression is extremely heterogeneous, the utilization of both pharmacophores has been suggested, specifically, the utilization of heterodimeric radiotracer ligands able to target both PSMA and GRPr." (PMID 39380961, 2023).
tumor (continued). "Our results indicate that PSMA-targeting applications, in contrast to GRPR, may not always distinguish cancerous tissue from benign or normal tissue, reducing the tumor-specific value." (PMID 37719014, 2023). "μSPECT/CT studies with the 99mTc-labeled MJ9 derivatives at 1 h p.i. in PC-3 tumor-bearing mice confirmed the biodistribution data, with [99mTc]Tc-N4-asp-[Bta8]MJ9 displaying the highest tumor-to-abdomen contrast at 1 h p.i. due to a rapid clearance from GRPR-positive pancreas and stomach." (PMID 36145354, 2022). "In vivo, [64Cu]Cu-NOTA/NODAGA-PEG2-RM26 bound specifically to GRPR-expressing tumors with fast clearance from blood and normal organs and displayed generally comparable biodistribution profiles to [57Co]Co-NOTA/NODAGA-PEG2-RM26; tumor uptake exceeded normal tissue uptake 3 h p.i.." (PMID 33352838, 2020). "Moreover, probes targeting VEGFA, GRPR, and αvβ3 showed positive signal in normal tissue and false-negative tumor detection in early-phase clinical trials." (PMID 32990883, 2020). "We hypothesized that the residualizing properties of the label for GRPR antagonist are not critical for a good tumour retention but a non-residualizing label would provide quicker clearance from normal tissues." (PMID 31382362, 2019). "Taking into account that tumor activity uptake could not be blocked with the co-injection of anti-GRPR binder alone, we concluded that the new heterodimer binds to both PSMA and GRPR." (PMID 31540122, 2019). "However, monitoring temporal and spatial expression of GRPR in vivo by clinical MRI is severely hampered by the lack of contrast agents with high relaxivity, targeting capability and tumor penetration." (PMID 26577829, 2015). "Therefore, our data suggest that GRPR expression in surrogate tissues did not reflect tumor burden and, perhaps, was not a direct consequence of the prevalent cancer." (PMID 22296774, 2012). "Thus, GRPR imaging could serve as a valuable adjunct, especially for PSMA‐negative tumours." (PMID 40265741, 2025). "Thus, 68Ga-DATA5m-RM2 offers a superior tumor-to-organ ratios, together with its much milder radiolabeling procedure, it might be a more viable candidate for further development as a PET agent for visualizing GRPr-positive tumors." (PMID 37285007, 2023). "Moreover, the receptor activation has been found to stimulate the tumor cells to invade and migrate to healthy tissues via one of the Gα proteins or transesterification of the epidermal growth factor receptor (EGFR), which is said to influence the GRPR-stimulated DNA synthesis in tumor cells." (PMID 36834867, 2023). "In another recent approach, one or more peptide bonds have been substituted by their triazolyl isosteres to improve the metabolic stability of resulting GRPR-directed radiopeptides, but again tumor uptake in animal models could not be significantly improved as compared with the non-modified analogs." (PMID 34830920, 2021). "It was later realised that, despite poor internalisation, GRPR antagonists might be advantageous over GRPR agonists because of the lack of pharmacological effects and better tumour-to-background ratios, through a higher number of binding sites or a higher affinity." (PMID 30543050, 2018). "In human cutaneous melanoma, GRPR levels correlated with YAP1 activation scores, and mouse ∆Ecad female tumours showed a YAP1 signature that was absent in ∆Ecad male or Ecad tumours." (PMID 40500450, 2025). "Tissue lysates of GRPR+ tumors showed no bands (columns 7 and 9 from left), but also CHO-K1-PSMA tumor lysates displayed PSMA bands with notably reduced intensity (columns 8 and 10 from left)." (PMID 40732291, 2025). "Notably, during NEP inhibition, the specificity of tumor uptake could be clearly illustrated in the significant reduction in the animals treated with single NT (for NTS1R-blockade), [Tyr4]BBN (for GRPR-blockade) or double-receptor ligand (s) (NT+[Tyr4]BBN for NTS1R/GRPR-blockade)." (PMID 39339259, 2024).
tumor (continued). "Regarding the [177Lu]Lu-NeoB therapeutic potential here, it seems to be at least similar if not better than others 177Lu-radiolabeled GRPR antagonists, such as [177Lu]Lu-JMV4168, which was evaluated in PC-3 tumor bearing mice." (PMID 33801382, 2021). "When GRPR in xenografts was blocked by co-injection of non-labeled maSSS-PEG2-RM26, no uptake of [99mTc]Tc-maSSS-PEG2-RM26 in PC-3 tumor was observed." (PMID 33573232, 2021). "Flow cytometric analysis showed no statistical significance of tumor cell uptake for NGO-BBN-AF750 and AF750-6Ahx-Sta-BBN, indicating little adverse effect of NGO on the BBN binding to GRPR on HSC-3 cells." (PMID 32651409, 2020). "For example, in the lesion of patient 1, which expressed GRPR but no integrin αvβ3, 99mTc-3P4-RGD2 imaging was unable to detect the tumor because it only recognized integrin αvβ3." (PMID 25849333, 2015). "Formal correlation analysis between GRPR immunohistochemical scores (IRS) and tumor uptake (SUVmax) on SPECT imaging could not be performed due to variability in administered doses across patients." (PMID 41155959, 2025). "This is likely due to insufficient or absent GRPR expression or the limited resolution obtainable by 99mTc-based SPECT imaging, alternatively a local recurrent tumour manifestation might have been masked by bladder activity." (PMID 38668903, 2024). "Furthermore, GRPR-related blocking of the tumor uptake of 8 and 10 in PC3 tumors was not successful, indicating an unspecific tumor uptake mechanism." (PMID 32751666, 2020). "PC3 tumor uptake of 64Cu/NOTA-dimer 2 was modestly lowered from 6.28 ± 2.87%ID/g to 3.25 ± 1.15%ID/g following the co-injection of the non-labeled peptide, again, indicating a GRPR dependant response." (PMID 22333272, 2012). "By co-injection with an excess of non-labelled peptide, tumour uptake was significantly (p < 0.05) reduced from 13 ± 5% ID/g to 1 ± 0% ID/g for [111In]In-DOTA-PEG2-RM26 and from 7 ± 1% ID/g to 5 ± 1% ID/g for [125I]I-Tyr-PEG2-RM26, indicating specific GRPR-mediated uptake." (PMID 31382362, 2019).
cancer (164 papers, 2003 to 2026). A tumor composed of atypical neoplastic, often pleomorphic cells that invade other tissues. "GRPR is widely expressed in various cancers, and its association with poor prognosis in cancer patients is well established." (PMID 39768218, 2024). "The discovery of high-affinity GRPR in cancers led to the creation of diagnostic, radiation, and chemotherapeutic reagents." (PMID 34943797, 2021). "Gastrin Releasing Peptide receptor (GRPr)-based radioligands have shown great promise for diagnostic imaging of GRPr-positive cancers, such as prostate and breast." (PMID 33258012, 2020). "This combination renders GRPR an appealing biomolecular target for directing diagnostic/therapeutic radionuclide-carriers specifically onto cancer lesions in a personalized theranostic approach." (PMID 30871262, 2019). "GRPR bronchial expression was also associated with smoking status among cancer-free surgical controls with an overrepresentation of GRPR bronchial expression among active smokers (P = 0.02)." (PMID 22296774, 2012). "This study introduces a sex-specific strategy that could improve cancer treatment in women in whom loss of E-cadherin leads to ERα and GRPR expression." (PMID 40500450, 2025). "A secondary aim was to investigate if PSMA and GRPR expression could be used to correctly classify each of the individual investigated on their PC cancer risk." (PMID 33854977, 2021). "Elevated GRPR expression in the lung may independently contribute to increased cancer risk by promoting proliferation." (PMID 22296774, 2012). "Gastrin-releasing peptide receptor (GRPR) is highly expressed in a variety of cancers and has also become an important target group for dual-modality probes." (PMID 41556044, 2026). "The gastrin-releasing peptide receptor (GRPR) is expressed across multiple human cancer types, including head and neck tumors, and has also been detected in the oral mucosa of patients bearing head and neck neoplasms." (PMID 41266536, 2025). "The overexpression of tumor-specific peptide receptors—such as the gastrin-releasing peptide receptor, natriuretic peptide receptor, and somatostatin receptor—in cancer cells offers an ideal molecular basis for targeted imaging and therapeutic approaches." (PMID 41300900, 2025). "The results demonstrate that UniCAR T-cells are specifically activated and upregulate CD69 in the presence of GRPR-expressing cancer cells (PC3 or LNCaP) and the BBN2 TMs." (PMID 40141329, 2025). "Given that the overexpression of GRPR in cancer cells facilitates the selective targeting of cytotoxic drugs, HPMA copolymers effectively minimize BBN consumption during delivery, thereby enhancing the tumor-targeting potential." (PMID 40305357, 2025). "Neurotensin receptor 1 (NTS1) and Gastrin‐Releasing Peptide Receptor (GRPR) are both G‐protein coupled receptors with complementary profile of expression in several cancer types." (PMID 39908060, 2025). "Agents targeting FAP, hypoxia, GRPr, and integrins are among those that have progressed furthest in clinical trials due to their excellent avidity for tumors and pan-cancer targeting properties, and are poised to enter clinical use soon." (PMID 40863874, 2025). "Our findings revealed that 58 (72.5%) cancer samples were GRPR-positive (GRPR+), and 22 (27.5%) were GRPR-negative (GRPR-)." (PMID 41266536, 2025). "While 68Ga-RM2 has emerged as the lead GRPr imaging agent, others have been developed and demonstrated similarly excellent cancer imaging characteristics, including 64Cu-Sarcophagine–Bombesin (64Cu-SAR-BBN)." (PMID 40863874, 2025). "In vitro assays were conducted using prostate (PC-3) and breast (MCF-7, and MDA-MB-231) cancer cell lines, all known to express GRPR." (PMID 40869454, 2025). "Recent reports also showed a promising use of GRPR ligands for imaging of gastrointestinal stromal tumors, rendering radiolabeled GRPR-targeted compounds promising for theranostic applications in different cancers." (PMID 40890559, 2025).